NTRK1 (neurotrophic receptor tyrosine kinase 1)
Diseases named in the same sentence as NTRK1 in open-access papers (continued):
Sharing a sentence is not in itself a finding about the gene and the disease.
tumor (continued). "These tumors are driven by fusions involving NTRK1, NTRK2, or NTRK3 with various partner genes, producing constitutively active TRK fusion proteins that promote tumor growth." (PMID 41463261, 2025). "Three of the fusion partners among adults with CRC harboring an NTRK gene fusion tumor have been commonly reported in the literature, including TPM3::NTRK1, TPR::NTRK1, and LMNA::NTRK1." (PMID 38967220, 2024). "The case of patient #8 (2 y/F), who had a TPM3::NTRK1-fused spinal HGG, highlights the potential efficacy of TRK inhibitor (larotrectinib) therapy in the management of recurrent and challenging tumours." (PMID 39014476, 2024). "This study showed that, across all tumor types, most NTRK fusion genes involved NTRK1 (49.5%) or NTRK3 (44.2%)." (PMID 38925616, 2024). "Nine tumors harbored an NTRK1 fusion with different fusion partners (4 × TPM3, 4 × LMNA, 1 × SFPQ), one tumor harbored an ETV6::NTRK3 fusion." (PMID 37067589, 2023). "All NTRK-rearranged neoplasms are characterized by immunohistochemical positivity for CD34 and S100 and, molecularly, by fusions of NTRK1, NTRK2, and NTRK3 genes with variable partners; alternative RAF1 and BRAF fusions have also been described." (PMID 37876963, 2023). "Chromosomal translocations involving the neurotrophin receptor tyrosine kinase genes NTRK1, NTRK2 or NTRK3 lead to TRK gene fusions, resulting in the overexpression of the proteins, their constitutive activation and subsequent tumour growth." (PMID 35954393, 2022). "Recent discoveries pointed out that these neoplasms, with a clinical course that differs from their pediatric and adult counterparts, carry specific molecular alterations, namely kinase (ALK, NTRK1/2/3, ROS1, or MET) gene fusions." (PMID 35565372, 2022). "Results suggested that the tumor carried a fusion of exons 1–8 of the KHDRBS1 gene and exons 12–17 of the NTRK1 gene." (PMID 33941195, 2021). "NTRK1, NTRK2 or NTRK3 can be found as oncogenic drivers in a wide range of paediatric and adult tumours." (PMID 33620682, 2021). "AR-tropomyosin receptor kinase (TRK) crosstalk mediated through nerve growth factor (NGF) also promoted tumor growth in ARSI challenged PCa cell lines, and are targetable by NTRK1/TRKA inhibitors." (PMID 34771580, 2021). "Fusions of neurotrophic tropomyosin receptor kinase genes NTRK1, NTRK2 and NTRK3 with various partner genes have been detected in a variety of both common and rare tumour entities." (PMID 34372873, 2021). "Ninety percent of the tumours with these gene rearrangements were native KRAS, with a high proportion of MSI-H: 86.4%, 45.5% and 14.3% of the tumours with NTRK1, RET and ALK fusions, respectively." (PMID 32418154, 2020). "Forty-four unique fusions were identified in 40 (1.1%) of the 3,808 patients with circulating tumor DNA detected: RET (n = 6; 36% of all fusions detected), FGFR3 (n = 2; 27%), ALK (n = 10, 23%), NTRK1 (n = 3; 7%), ROS1 (n = 2; 5%), and FGFR2 (n = 1; 2%)." (PMID 33015522, 2019). "These tumours have been provisionally named LPF-like neural tumours and are defined by NTRK1 oncogenic activation." (PMID 31738427, 2019). "Similar to ALK and ROS1 rearrangement, fusions of NTRK1, NTRK2, and NTRK3 are actionable drivers of tumor growth." (PMID 31023335, 2019). "These fusions were both confirmed to be tumour-specific and preserved the tyrosine kinase domain in the 3′ fusion partners RET and NTRK1, respectively." (PMID 31653970, 2019). "The neurotrophic tyrosine kinase receptor TrkA (NTRK1) and its ligand nerve growth factor (NGF) are emerging promoters of tumor progression." (PMID 29802376, 2018). "In every tumor that exhibited EGFR, PDGFRA, NTRK1, MDM2, MDM4, or CDK4 amplification, the increased copy number was contained within, or contained translocations into, a suspect chromothriptic region." (PMID 26328271, 2015).
tumor (continued). "For example, we found six cancer types with a single fusion in a gene of the NTRK family, but altogether, we detected a total of 23 NTRK1, NTRK2 and NTRK3 fusions across nine tumour types." (PMID 25204415, 2014). "We previously demonstrated that the low expression of favorable NB genes (EFNB2, EFNB3, EPHB6, NTRK1, CD44 and MIZ-1), as well as that of the tumor growth suppressive gene, EPHA2, in NB cell lines was due to epigenetic silencing." (PMID 24190252, 2014). "Nervous system developmental genes, including NTRK1 and DBH were found to be highly expressed in the favourable tumour cluster h1." (PMID 21492432, 2011). "Tumour markers such as MYCN amplification, histology, ploidy, and NTRK1 expression have proven prognostic value in large cohorts of NB patients." (PMID 19192278, 2009). "In the group of genes that shows high expression in tumours with favourable outcome, genes related to cell differentiation (FYN, NTRK1) and neuronal development (DCAMKL1) can be found." (PMID 17531100, 2007). "summarized the role of NTRK1, NTRK2, and NTRK3 gene rearrangements in different tumor types." (PMID 41275415, 2025). "Specifically, NTRK1 expression was significantly higher in right-sided tumours, late pathological T stage, non-metastasis (M0) stage, MSI positive state, the hypermutated/MSI subtype, BRAF mutation-positive, low FGA state, low aneuploidy state and high TMB." (PMID 41155675, 2025). "Finaly, the tumor mutational burden (TMB) was low, and no abnormalities were detected in BRAF, NRAS, HRAS, NTRK1/2/3, RET, or TERT." (PMID 40277780, 2025). "The identification of NTRK1 and NTRK2 upregulation among patients diagnosed with ER+ BC implies that upregulation in ER+ patients may play a role in facilitating tumour survival or growth within this subtype." (PMID 40061872, 2025). "The upregulation of both NTRK1 and NTRK2 could imply that it contributes to the progression of PR+ tumours or affects their response to hormonal therapies." (PMID 40061872, 2025). "Somatic intrachromosomal or interchromosomal rearrangements involving NTRK1, NTRK2, or NTRK3 may be found as oncogenic drivers in a wide range of tumor types." (PMID 39295960, 2024). "Additionally, gene fusions involving neurotrophin receptor tyrosine kinases, encompassing NTRK1, NTRK2, and NTRK3, lead to overexpression and constitutive activation of these genes and subsequent tumor growth." (PMID 39668367, 2024). "All cases showing NTRK1 rearrangement in <15% of tumor cells analyzed were negative by RT‐PCR and NGS." (PMID 37143440, 2023). "Named based on the expression of previously established marker genes ERBB2 (T062), NTRK1 (T063), MYCN (T064) and TERT (T065), these subtypes may be rooted in the tumor’s lineage." (PMID 36932241, 2023). "Three cases showed NTRK1 rearrangement in approximately 7% of tumor cells analyzed, but this percentage was not sufficient to indicate positivity." (PMID 37143440, 2023). "Regarding the FISH threshold, the two cases with pan‐TRK IHC positive (intensity score 1+) and NTRK1 FISH showing about 7% of tumor cells rearranged were negative by NGS." (PMID 37143440, 2023). "To investigate whether VIRMA exerts its tumor-promoting function through upregulating ITGA2, ITGA5, and NTRK1 expression, we performed in vitro functional experiments by overexpressing ITGA2, ITGA5, or NTRK1 in VIRMA-silenced NPC cells." (PMID 37028765, 2023). "E2F7 cooperated with CBFB-recruited RUNX1 in a non-canonical manner to transactivate ITGA2, ITGA5, and NTRK1, strengthening Akt signaling-induced tumor-promoting effect." (PMID 37028765, 2023). "There were 20 (48.8%) NTRK1 and 21 (51.2%) NTRK3 fusions in 7 and 12 tumor types, respectively." (PMID 37567953, 2023). "Our findings suggest that growth factors in the tumor microenvironment, such as HGF, may induce resistance to entrectinib in tumors with NTRK1 or ROS1 rearrangements." (PMID 36416133, 2023).
tumor (continued). "All cases that showed NTRK1 split‐apart signals less than two signals in diameter in approximately 5–15% of tumor cells were negative by RT‐PCR and NGS." (PMID 37143440, 2023). "Polyploidy was detected in most tumor cells using the NTRK1 break-apart probe in case #6, but no rearrangement of NTRK1, NTRK2, or NTRK3 was detected using the three break-apart probes." (PMID 36612101, 2022). "Evidence can also be found in another study of 91 NSCLC patients, of which the tumor with NTRK1 gene fusions had no known oncogenic alterations." (PMID 35372074, 2022). "The results showed that approximately 11% of cells were 0r-1Gr-1Fu, which did not support the existence of NTRK1 rearrangement (NTRK1 gene signal was mostly 1-3FU) in the tumor." (PMID 35572973, 2022). "NTRK1/2/3 fusion gene detection is independent of tumor type and follows the European Society for Medical Oncology (ESMO) recommendations." (PMID 35743191, 2022). "In order to show that the anti-tumor effect of AZD4547 against KM12(Luc) is caused by inhibition of TRKs rather than FGFR, we monitored mRNA levels of FGFR1/2 and NTRK1/2 in KM12(Luc)." (PMID 34790577, 2021). "Fusions of neurotrophic tropomyosin receptor kinase genes NTRK1, NTRK2 and NTRK3 with various partner genes occur in both common and rare tumours and are of paramount predictive value due to the availability of very effective pan-Trk inhibitors like Larotrectinib and Entrectinib." (PMID 34372873, 2021). "IL7R, NOX2-1, and NTRK1 were more frequent in CSF but not that frequent both in tumor tissues and plasma." (PMID 34671549, 2021). "Furthermore, mutually exclusive expression of the neurotrophic receptor tyrosine kinases 1 or 2 (NTRK1, NTRK2) has prognostic significance, and both kinases contribute to distinct neuroblastoma biologies, in particular to differences in tumor immunogenicity." (PMID 32296437, 2020). "More recently, NTRK1 chromosomal rearrangements have been identified in additional tumor types, suggesting that while oncogenic activation through NTRK1 fusion is not frequent, it can occur in various cancers." (PMID 32957984, 2020). "p75NTR in HNSCC might be related with NGF-independent therapy resistance, while NTRK1 might transduce a survival signal of NGF and contribute in this way to improved tumor cell survival after cell cycle arrest." (PMID 29904026, 2018). "Bcan-Ntrk1-induced tumors showed elevated percentage of Ki67-positive cells, were positive for OLIG2 and NESTIN, negative for the neuronal marker NeuN and GFAP-positive cells were almost exclusively detected at the normal/tumor border." (PMID 29654229, 2018). "The synthesis of these two receptors is separated to two cell populations in the HNSCC tumor cell nests: high levels of NTRK1 and p75NTR were not present in the same cells of HNSCC tumor tissue and cultured cell lines." (PMID 29904026, 2018). "However, despite durable responses in pediatric patients with intracranial tumors or NB harboring NTRK1/2/3 or ROS1 fusions, its utility may be hampered by the appearance of acquired resistance in this tumor type." (PMID 36839989, 2023). "Since NTRK1 is a target of EGR1, the central hub involved in NAB2-STAT6-dependent deregulation of gene expression, our results may suggest that an increased EGR1 transcriptional program could lead to a more aggressive tumor phenotype." (PMID 34680383, 2021). "This tumor was reported to have a mitotic index of 4 per 10 high-power fields without nuclear atypia or necrosis and an LMNA::NTRK1 fusion." (PMID 40491214, 2025). "In addition, the poorly differentiated thyroid carcinoma presented faint cytoplasmic pan-TRK staining in less than 5% of isolated tumor cells by IHC and negative FISH results for NTRK3, NTRK1 and NTRK2." (PMID 40338900, 2025). "Thus, fusions in ROS1, RET, NTRK1 and amplifications in MET, ALK, EGFR, for example, may not be detected with circulating DNA and RNA, notably during tumor progression under treatment with TKI targeting ALK rearrangements." (PMID 33467720, 2021).
cancer (426 papers, 2006 to 2026). A tumor composed of atypical neoplastic, often pleomorphic cells that invade other tissues. "NTRK1 fusions lead to constitutive kinase activity and have been implicated in various cancers, including radon-induced lung cancer." (PMID 40427695, 2025). "This study also showed that high NTRK1/2/3 expression was associated with enrichment of known cancer signalling pathways." (PMID 41155675, 2025). "It is primarily expressed in the brain and adrenal glands, and mutations in NTRK1 are associated with various cancers and pain insensitivity." (PMID 40502754, 2025). "Scenarios include NTRK fusion genes, such as NTRK1, NTRK2, and NTRK3 (encoding tropomyosin receptor kinases, TrkA, TrkB, and TrkC, respectively), that link the tyrosine kinase domain with a 5’ fusion partner (over 50 partners across cancers)." (PMID 39956859, 2025). "NTRK fusion-positive cancers, specific mutations in the kinase domain, such as NTRK1 G595R and NTRK3 G623R, have been implicated in resistance by altering TKI binding affinity." (PMID 39518080, 2024). "Since TrkA is a receptor with tyrosine kinase activity, tyrosine kinase inhibitors have been developed to block TrkA activation associated with an NTRK1 fusion or TrkA overexpression in cancers." (PMID 37046604, 2023). "NTRK1, a gene encoding for TRKA, is a particularly attractive target for cancer therapy, owing to its status as a critical protein in carcinogenesis." (PMID 35747831, 2022). "As for the association between the NTRK genes and diseases other than malignant tumors, congenital insensitivity to pain with anhidrosis type IV, a hereditary disease, has a pathological variant of the NTRK1 gene." (PMID 31974683, 2020). "ROS1 G2032R is also analogous to the G595R mutation in NTRK1 identified in entrectinib-resistant NTRK1-rearranged cancer." (PMID 31399568, 2019). "The most common NTRK1 alterations observed in cancer are gene fusions; however, point mutations have also been reported in numerous solid tumors." (PMID 29383146, 2017). "Herein, the lower gene expression of NTRK1 in the cancer tissues might indicate suppression of its associated pathways leading to cancer." (PMID 38635549, 2024). "The kinase domain of NTRK1 is found fused with potentially many other proteins and these fusions form a diagnostic pattern for some rare cancers and are a relatively low but consistent occurrence for more common cancers." (PMID 38022692, 2023). "LMNA::NTRK1 fusion has also been implicated as the driver pathogenetic event in a wide spectrum of tumors of various lineages and risk of malignancies, including carcinomas, melanocytic Spitz lesions, as well as benign and malignant mesenchymal neoplasms." (PMID 36801905, 2023). "In addition, carcinomas cases harboring NTRK1 rearrangement were associated with multifocal and aggressive tumors." (PMID 35860155, 2022). "In silico and data-mining analyses suggest that FAM171A1 has been predicted to interact with FAM171B, PCDHGB1, TNFRSF17, TMEM, CTDSPL, and NTRK1, many of which have been already implicated in various cancers suggesting most likely its possible role in the tumorigenesis." (PMID 30631046, 2019). "A number of splice variants have been characterised, particularly involving NTRK1, and these variants have been observed both in normal tissues and in human cancers such as neuroblastoma and acute myeloid leukaemia where it is thought that they may play a role in tumourigenesis." (PMID 31738428, 2019). "NTRK fusions, which result from rearrangements in the NTRK1, NTRK2, or NTRK3 genes (encoding TRKA, TRKB, and TRKC, respectively), are actionable oncogenic drivers found in a diverse range of adult and pediatric cancers." (PMID 41492362, 2026). "Inhibitors such as larotrectinib, entrectinib and repotrectinib are used when cancer cells harbor NTRK1, NTRK2 or NTRK3 fusion." (PMID 41744839, 2026).
cancer (continued). "The inhibition of the nerve growth factor (NGF)–neurotrophic tyrosine kinase receptor (NTRK1) pathway has been shown to inhibit cancer proliferation, reduce innervation and increase the overall survival of mice when treated together with gemcitabine." (PMID 40075699, 2025). "A total of 316 patients (21.1%) had a fusion detected (RET or NTRK1/2/3) with matched targeted therapy approved in all cancer indications." (PMID 41091579, 2025). "The TRK family kinases (encoded by NTRK1, NTRK2, and NTRK3) are activated in cancer by a range of mechanisms, including gene amplification, mutation, and gene fusions." (PMID 40348911, 2025). "These relationships are in keeping with the established oncogenic functions of NTRK1/2/3 in cancers generally." (PMID 41155675, 2025). "NTRK1 fusions are found in cancers across many different tissues, and the tyrosine kinase inhibitor larotrectinib is now used in patients positive for fusions involving NTRK1." (PMID 41421967, 2025). "In the final, we counted the genomic alterations of NTRK1/2/3 in the TCGA pan-cancer cohort in each patient." (PMID 38357305, 2024). "These investigations have also identified four potential EGCG target proteins linked to cancer development: IKBKB, KRAS, WEE1, and NTRK1." (PMID 38978121, 2024). "Gene fusions involving the NTRK1-3 genes have been identified as oncogenic drivers in various cancer types." (PMID 38902532, 2024). "In the present study, the expression of NTRK1 in various cancers and their related normal tissues was performed through the Expression Atlas." (PMID 38635549, 2024). "NTRK1-3 fusions are exceptionally rare in common cancer types; therefore, the feasibility of the use of individual NTRK1-3 tests is questionable." (PMID 38612902, 2024). "We detected fusion transcripts of the NTRK1/2/3 genes in pan-cancer through the TCGA Fusion Gene Database with high credibility." (PMID 38357305, 2024). "Finding BRAF mutations or PPARG, NTRK1, NTRK3 and ALK fusions were strong predictors of a higher risk of cancer (approaching 100%) while other mutations like RAS, PTEN and EIF1AX or THADA fusions were associated with a significant but lower risk of cancer." (PMID 37510219, 2023). "In particular, about 30% of pediatric cancers harbor BRAF/RAS mutations, while gene fusions are present in up to 60% of cases, mainly in younger patients with PTC, usually involving RET or NTRK1/3, as also ALK, BRAF and PPARG." (PMID 37046700, 2023). "NTRK1, NTRK2, and NTRK3 are genes encoding tyrosine kinase receptors and their fusions with other genes are frequent in some rare cancer types (e.g., secretory breast carcinoma), but in NSCLC the prevalence of these alterations is approximately 0.1–1%." (PMID 36291146, 2022). "NTRK1-rearranged carcinomas have been more aggressive with multifocality than NTRK3-rearranged carcinomas." (PMID 35625691, 2022). "Based on the single-cell sequencing data of HNSC, we found that CHRNB4 was mainly expressed in cancer cells, while NTRK1 was mainly expressed in mast cells." (PMID 34912722, 2021). "The results of NTRK1 level in cancer cell lines demonstrated that stress hormones inhibited NTRK1 expression." (PMID 34650925, 2021). "The carcinomas positive for NTRK1 fusions had a significantly more common mixture of papillary and follicular growth patterns (p = 0.006) than the carcinomas positive for NTRK3 fusions, which had mostly predominant follicular growth patterns." (PMID 33923728, 2021). "Other differences were the significantly higher frequencies of multifocality (p = 0.015), extrathyroidal extension (p = 0.008), intravascular invasion (p = 0.024) and distant metastases (p = 0.013) of NTRK1 fusion-positive carcinomas." (PMID 33923728, 2021). "The carcinomas harboring NTRK3 fusions (n = 49) were compared to the carcinomas with NTRK1 fusions (n = 10)." (PMID 33923728, 2021).